BGN (biglycan)
Diseases named in the same sentence as BGN in open-access papers (continued):
Sharing a sentence is not in itself a finding about the gene and the disease.
tumor (continued). "Although BGN expression in malignant tumor cells was lower than that in stromal populations, its expression in tumor cells remained notably high and should not be overlooked, particularly when compared to normal thyroid follicular cells, where BGN expression was significantly lower." (PMID 41328346, 2026). "Notably, PTC patients with high BGN expression secreted by malignant PTC cells demonstrated elevated immune scores and markedly reduced tumor purity compared to those with low BGN expression, suggesting a possible link between BGN and increased immune cell infiltration." (PMID 41328346, 2026). "These overlapping and sometimes opposing mechanisms indicate that biglycan may act as a fine modulator of tumour–stroma interactions rather than as a simple structural ECM component." (PMID 41463344, 2025). "Moreover, in macrophages, BGN promoted proliferation and migration, and induced M2-like polarization by activating the NF-κB signaling pathway through TLR4, suggesting its multifaceted role in modulating the tumor microenvironment." (PMID 41465449, 2025). "However, unlike decorin, endorepellin, endostatin and biglycan foster tumour angiogenesis in metastatic cancer via upregulating VEGFA levels and VEGFA–VEGFR2 signalling." (PMID 34982945, 2022). "Therefore, we investigated whether the expression of THBS2, FSTL3, TNNT1, BGN, CTHRC1, and NOX4 was correlated with immune cell infiltration levels in CRC via the Tumor Immune Estimation Resource (TIMER) database." (PMID 35127707, 2021). "Therefore, HER2-mediated silencing of biglycan expression may promote tumor cell proliferation and migration and provides a putative therapeutic target for the treatment of HER2+ tumor cells." (PMID 34917515, 2021). "However, we did not analyze the association between the BGN expression in fibrotic tissue and tumor progression because BGN is secreted from fibroblasts not only in tumor tissues but also in normal tissues." (PMID 33709550, 2021). "TECs‐biglycan activates nuclear factor‐κB (NF‐kB) and extracellular signal‐regulated kinase (ERK) signal transduction to stimulate the metastasis of tumor cells expressing toll‐like receptors (TLR) and promote tumor angiogenesis of tumors by activating the TLR signaling pathway." (PMID 34977870, 2021). "In addition, BGN and MMP1 were both upregulated in the epithelial tumor cells." (PMID 28687755, 2017). "In contrast, tumour cell adhesion to a monolayer of biglycan-knockdown HM-TECs did not change." (PMID 27295191, 2016). "Biglycan-treated tumour cells showed significant increases in NF-κB activity, whereas this induction was attenuated by pretreatment with TLR2 and/or TLR4 inhibitors, suggesting that biglycan-induced tumour cell migration was mediated by NF-κB activation through TLRs." (PMID 27295191, 2016). "However, a recent study indicated that the expression of only decorin, but not the other related SLPRs such as asporin and biglycan, varied between tumor and normal tissues." (PMID 26379028, 2015). "Biglycan was stained in tumour blood vessels, but not or weakly stained in normal blood vessels." (PMID 22374465, 2012). "However, the role of biglycan in tumor stroma has not been clarified." (PMID 33966638, 2021). "In addition, biglycan, through interaction with TLR2/4 receptors on the surface of macrophages, promotes inflammation by triggering the synthesis of two cytokines important for cancer progression, TNFα and CCL2, and thus enhances tumor growth in many cancer cells." (PMID 32847060, 2020). "Moreover, decorin, but not biglycan, could inhibit the metastasis of the targeted tumor cells through transgenic delivery." (PMID 26379028, 2015). "In contrast, versican and biglycan PGs, other matrix-secreted PGs, accumulate in the peritumoural ECM, stimulate inflammatory pathways, and drive tumour invasion and early relapse in node-negative BC." (PMID 41463344, 2025).
tumor (continued). "Our results on protein expression using western blot assay also showed an increase in COL10A1, BGN, and FAP proteins in tumor tissue compared with adjacent normal tissue, consistent with staging." (PMID 35328635, 2022). "The results demonstrated that the tumour tissue was completely negative for DCN immunoreactivity, while BGN immunoreactivity was locally clearly detected." (PMID 28653173, 2017). "BGN expression in ESCC tissues was predominantly observed in the stroma, not within tumor nests." (PMID 41465449, 2025).
cancer (122 papers, 2007 to 2026). A tumor composed of atypical neoplastic, often pleomorphic cells that invade other tissues. "BGN is widely implicated in various malignancies and has been shown to influence immune cell function and therapeutic response in several cancers." (PMID 41328346, 2026). "In line with the importance of BGN for PC growth, a recent study showed that downregulation of BGN in cancer-associated fibroblasts (CAFs) suppresses their proliferation, migration, and invasion in vitro." (PMID 41470114, 2025). "In vitro experiments revealed significantly higher expression of BGN in cancer-associated fibroblasts (CAFs) compared to normal fibroblasts (NFs)." (PMID 38654221, 2024). "Downregulation of BGN expression in cancer-associated fibroblasts (CAFs) significantly reduces migration and proliferation of CRC cells." (PMID 38654221, 2024). "For instance, cancer-associated fibroblast-derived biglycan was confirmed having great potential acting as therapeutic target in immunotherapy." (PMID 37809080, 2023). "Recent research has shown that CAFs are closely associated with the response to immunotherapy in cancer patients, and has implicated biglycan, a CAF-derived proteoglycan in the ECM, in this association." (PMID 37174001, 2023). "BGN gene, encoding a small proteoglycan biglycan, was strongly upregulated in dormant cancer cells in vivo." (PMID 37456245, 2023). "This demonstrated that cancer cells that can proliferate in the brain and develop into large metastases are associated with reduced BGN expression levels in patients, in line with our data in a preclinical model." (PMID 37456245, 2023). "BGN has been associated with poor prognosis in several cancer types and seems to contribute to the EMT process." (PMID 36358747, 2022). "BGN overexpression in cancer cells is associated with phosphorylation of AKT, expression of mesenchymal markers, and liver metastasis." (PMID 36358747, 2022). "One of the major functions associated with biglycan expression in cancer is its potential to modulate cancer cell invasion, angiogenesis, and metastasis formation." (PMID 33809543, 2021). "Recently, BGN expression has been reported to be associated with prognoses of patients and cancer progression in various types of cancer." (PMID 33709550, 2021). "Context is surely critical, as BGN expression was induced in TGFβ treated cancer-associated fibroblasts (CAFs), implying involvement in generating a fibrotic stroma and an invasion permissive environment." (PMID 34449016, 2021). "We found that the gene signature associated with BGN expression was enriched in cancer-associated pathways, such as regulation of cytoskeleton, cell migration, apoptosis, ECM adhesion, and structural organization and angiogenesis." (PMID 33809543, 2021). "One of the major functions that is associated with biglycan in cancer is its potential to modulate cancer cell angiogenesis and metastasis formation." (PMID 33809543, 2021). "Additionally, the previous study unraveled that biglycan derived from the cancer-associated fibroblasts served as a potential therapeutic target in immunotherapy resistance in TNBC." (PMID 40524231, 2025). "Accordingly, a more recent gene expression study supported the potential involvement of BGN in the crosstalk between PC cells and stromal cells; namely, the study suggests that the BGN gene is also a part of a cancer-associated-fibroblasts (CAFs)-related prognostic model in PC." (PMID 41470114, 2025). "Some reports have revealed that BGN expression in serum is linked to the malignancy of cancer." (PMID 39578715, 2024). "To investigate whether biglycan is functionally implicated in the regulation of cancer cell growth in vivo, we generated MDA-MB-231 cells stably expressing BGN (MDA-MB-231/BGN) under the control of a doxycycline-inducible promoter." (PMID 37456245, 2023). "Next, we analyzed the association between BGN expression and TIICs across human cancers." (PMID 34868341, 2021).
cancer (continued). "It is conceivable that the regulation of BGN in cancer is closely associated with inflammation." (PMID 31739592, 2019). "Biglycan secreted from TEC into blood flow might be of diagnostic value in various malignant tumours." (PMID 22374465, 2012). "Thus, high expression of biglycan is associated with high stemness in cancer cells." (PMID 32821344, 2020). "Integrated analysis of GSE250521 and GSE193581 revealed that BGN+ cancer cells exhibited more frequent and stronger interactions with M2 macrophages among all TME cell types." (PMID 41328346, 2026). "Additional roles of biglycan in cancer include the regulation of angiogenesis through the upregulation of VEGFA expression, accompanied by elevated HIF and reactive oxygen species levels in a TLR2/4-dependent manner." (PMID 41463344, 2025). "BGN has been reported to act as a secreted protein with pro-tumorigenic effects in several cancers, and in this study, we investigated its functional role in ESCC progression." (PMID 41465449, 2025). "Previous studies have suggested that Biglycan appears to have a dual role depending on the cancer type." (PMID 39155517, 2025). "In this study, we identified BGN as a new CAF-derived soluble factor by focusing on genes that showed low expression in cancer cells but showed specific expression increases in CAFs in a direct co-culture model." (PMID 41465449, 2025). "While BGN has been extensively studied in other cancers, its expression and functional involvement in ESCC have remained largely unexplored." (PMID 41465449, 2025). "Members of the SLRP family (mainly biglycan, lumican, and decorin) modulate cancer cell functions such as proliferation, migration, adhesion, and invasion in several cancer types." (PMID 39334952, 2024). "The expression of biglycan (BGN), a TLR4 ligand, is elevated in cancers, contributing to the epigenetic silencing of siglec-7 ligands through the BGN/TLR4/NF-κB pathway in CRC cells." (PMID 38930793, 2024). "As BGN was one of the top most over-represented proteins in the carcinoma signature, western blot was performed on new, independent EV isolates, which confirmed higher abundance of BGN in the carcinoma EVs." (PMID 39462388, 2024). "In pancreatic cancer, biglycan is overexpressed, leading to the inhibition of TGF-β1-responsive and -unresponsive cancer cells through induction of G1-arrest, associated with an increase in p27 and reduction in cyclin A and proliferating cell nuclear antigen." (PMID 36765749, 2023). "The most significantly differentially expressed gene was BGN (FDR 1.7x10-100), which encodes a small extracellular matrix protein biglycan, with 474-fold upregulation in dormant versus proliferating cancer cells." (PMID 37456245, 2023). "This review will focus on the functions of the class I and II SLRP members biglycan and lumican, which are correlated to various aspects of cancer development." (PMID 37509212, 2023). "As an important component of ECM proteins, BGN seems to play an important role in the oncogenesis and progression of various cancers." (PMID 35938042, 2022). "The expression of BGN in GC (375 cases from TCGA) was significantly higher than in normal tissues (32 para-cancer tissues from TCGA and 174 normal tissues from GTEx) (p < 0.001)." (PMID 35154268, 2022). "Some SLRP family members are known substrates of MMPs, and Type-I SLRPs, such as Decorin and Biglycan have been reported to affect cancer progression." (PMID 36230849, 2022). "Concordantly, high BGN expression was detected in MCF-7 derived CD24−/CD44+ BCSCs as compared to their respective bulk cancer cells." (PMID 35053617, 2022). "In some malignant tumors, higher expression of BGN predicts more considerable invasiveness and worse prognosis." (PMID 36110576, 2022). "These pro-autophagic effects of biglycan have yet to be explored in the extracellular milieu of cancer." (PMID 34982945, 2022). "Significant differential expression of BGN was documented in most of the 33 cancers, including in STAD." (PMID 35154268, 2022).
cancer (continued). "Depletion of BGN in luminal cancer cell lines suppressed the enrichment of CSCs and tumorsphere formation." (PMID 35053617, 2022). "Using the in vivo angiogenesis CAM model, we found that biglycan KO cancer cells lead to a decrease in the number of blood vessels when compared with WT tumors." (PMID 33809543, 2021). "Meanwhile, we observed that BGN expression was significantly negatively related to B cells in more than 80% of cancer types." (PMID 34868341, 2021). "Similar to TSKU, decorin (DCN) and biglycan (BGN) are two key SLRPs that have altered expression in various cancers with diverse clinical outcomes, and BGN serves as a potential marker of cancer proliferation associated with poor clinical outcome." (PMID 33428594, 2021). "BGN has also been shown to promote the cancer invasion, EMT, angiogenesis, and chemotherapy resistance." (PMID 34590603, 2021). "Together, these results indicate that biglycan can modulate anti- and pro-apoptotic markers to sustain cancer cell viability while avoiding cell death." (PMID 33809543, 2021). "In the following sections, we will summarize and discuss the major signaling functions of biglycan and decorin in normal physiology and in the context of cancer." (PMID 34917515, 2021). "Our results set the ground for future research aiming to target biglycan in therapeutic approaches directed at tackling cancer progression." (PMID 33809543, 2021). "Biglycan (BGN gene), an extracellular proteoglycan, has been described to be associated with cancer aggressiveness." (PMID 33809543, 2021). "There were 377 BGN-expressing cells, of which only 10 were from normal tissues and 367 were from cancer tissues." (PMID 34899080, 2021). "Biglycan has also been detected in several types of human cancers cells, such as endometrial cancer, bladder cancer, and pancreatic adenocarcinoma." (PMID 33966638, 2021). "For further studies, the negative GC cell lines (NCI-N87 and MKN45) were also used to assess the role of exogenous biglycan in cancer aggressive features." (PMID 33809543, 2021). "Beside its role in cardiovascular diseases, biglycan is important for the mineralization of bones and is highly expressed in cancer with metastatic activity and lower survival." (PMID 34830059, 2021). "Biglycan promotes EMT in cancer cells, and its expression involves TGFβ/Snail and TNFα/NFkB signals." (PMID 32821344, 2020). "As this effect of MSCs on cancer cells disappears with their differentiation, it is thought that the maintenance of MSC stemness by biglycan is important for acquiring the metastatic potential of cancer cells." (PMID 32821344, 2020). "Cancer‐associated fibroblasts (CAFs), expressing extracellular matrix (ECM) genes such as COL1A1, LUM, and BGN, formed the larger cluster." (PMID 33332768, 2020). "Biglycan, lumican, and fibromodulin are overexpressed in various types of cancer, whilst decorin is overexpressed in some types of cancer and suppressed in others." (PMID 33202923, 2020). "Similar to biglycan, serum levels of endocan have been reported to be also higher in patients with cancers of the lung, kidney, and liver than in controls." (PMID 32375250, 2020). "We screened several TLR4 ligands and found that among them BGN is highly expressed in cancers and is involved in the epigenetic silencing of Siglec-7 ligands." (PMID 32050430, 2020). "There was a dramatic increase in mRNA levels of BGN in stage I cancer samples, and this was extremely statistically significant p < 0.001." (PMID 32050430, 2020). "Our data suggest that the action of biglycan is mediated by cell contact between cancer cells and MSCs." (PMID 32821344, 2020). "Various studies have shown that the upregulation of biglycan in cancer stroma is positively correlated with cell proliferation, migration, metastasis, and angiogenesis through the regulation of the TLR/NF-κB, MAPK, and the FAK signaling pathway." (PMID 31608236, 2019).